INS (insulin)
Diseases named in the same sentence as INS in open-access papers (continued):
Sharing a sentence is not in itself a finding about the gene and the disease.
Obesity (continued). "The suggestion that relatively high circulating insulin levels may protect against breast cancer risk before the menopause is consistent with the apparently protective effect of diabetes observed by others authors; and it resembles closely the situation seen in obesity." (PMID 34485137, 2021). "Nonetheless, insulin and glucose tolerance tests revealed significant obesity-related metabolic disorders in GPNMB-KO mice compared with WT mice fed with HFD." (PMID 34582891, 2021). "Despite the higher clamp insulin concentration in the groups with obesity, they had less responsiveness to insulin in substrate utilization, further supporting our conclusions." (PMID 33616083, 2021). "Obesity also mediates increase in pancreatic insulin production and peripheral tissue insulin resistance." (PMID 34621189, 2021). "We sought to determine putative relationships among mitochondrial function, insulin sensitivity and altered skeletal muscle lipids and metabolites in response to an exercise intervention in black South African women with obesity." (PMID 33770195, 2021). "It is well established that CR and exercise improve insulin sensitivity in humans with overweight or obesity, while little significant effect of CR on insulin sensitivity in normal weight individuals was reported by previous studies." (PMID 34579097, 2021). "While initially insulin sensitivity was comparable between obese and normal children, early in the evolution of obesity, both insulin and C-peptide secretion to a normal meal were found increased in obese children compared to normal children." (PMID 34360563, 2021). "Hyperinsulinemia promotes further obesity because insulin is an anabolic hormone that promotes glucose uptake and fat storage." (PMID 34463983, 2021). "One mechanism believed to contribute to obesity’s role in cancer is the increase in adipocytes in the body, which can increase circulating levels of insulin and Insulin Growth Factor 1 (IGF1) hormones." (PMID 34068325, 2021). "Whereas beta-cells seem to compensate for high insulin demand that occurs in obesity, when the compensation mechanisms are lost and beta-cells become exhausted, hyperglycemia appears." (PMID 34069914, 2021). "In the equine, however, results from research assessing the role of exercise in managing obesity and insulin resistance are variable, and there are limited investigations into how exercise affects the metabolism of native breed horses and ponies specifically." (PMID 34048478, 2021). "In line with other studies, IL-1β was co-expressed with other genes of insulin-related pathways across tissues in metabolically unhealthy obese compared to metabolically healthy obese people, indicating a potential role in obesity." (PMID 33803198, 2021). "Obesity-related dysfunction can contribute to cancer pathogenesis and treatment resistance through various mechanisms, including those mediated by insulin, leptin, adipokine, and aromatase signalling pathways, particularly in women." (PMID 33911195, 2021). "The activation of UCP-1 provides benefits against obesity, decreases fat mass, and improve insulin sensitivity." (PMID 34721992, 2021). "When iRhom 2 is knocked out, those mice fed upon HFD had a mitigation of obesity, insulin resistance and chronic adipose tissue inflammation in comparison with that in mice with iRhom 2 overexpression." (PMID 33904577, 2021). "The efficacy of NR supplementation in obesity and insulin sensitivity is being tested (US National Library of Medicine, 2016a, b), and no adverse effects have been reported." (PMID 33833691, 2021). "Treatment with obesity-related harmful strains increases the hypertrophy of adipocytes in obese mice, resulting in decreased insulin sensitivity and increased lipolysis in adipose tissue." (PMID 34366839, 2021).
Obesity (continued). "Many studies have demonstrated that both fasting and the postprandial enhancement of ATBF are impaired in obesity and insulin-resistant conditions, thereby contributing to the metabolic perturbations in insulin-resistant individuals with obesity." (PMID 33591224, 2021). "In recent reviews, we have described the role of elevated endogenous insulin levels in the development of obesity and arteriosclerosis." (PMID 34879839, 2021). "One proposed mechanism linking obesity and breast cancer recurrence are elevated insulin levels and reduced insulin sensitivity." (PMID 34578984, 2021). "Predominantly expressed in the visceral depot, omentin -34 kDa- is an anti-inflammatory adipokine with insulin-sensitizing effects whose levels are decreased in obesity and diabetes and inversely correlated BMI." (PMID 34884217, 2021). "Research over the past two decades has uncovered an important role for extracellular LPA signaling and the LPA-metabolizing enzymes, ATX and LPP3, in energy homeostasis, insulin function, and obesity-induced metabolic complications." (PMID 34502491, 2021). "In this long-term study, we found that patients with high fasting plasma glucose (FPG) and insulin requirement during pregnancy are at an increased risk of developing T2DM, while pregestational obesity is predictive of progression to MetS." (PMID 33021758, 2021). "Visceral fat is the key adipose compartment linking obesity to carcinogenesis, through increased systemic inflammation, insulin resistance, IGF-1, and immune cell alterations, as well as promoting inflammation in the TME." (PMID 33777773, 2021). "Increasing adiponectin levels is an important therapeutic goal given that it improves insulin sensitivity, reduces inflammation, and improves metabolic function in obesity models." (PMID 34231322, 2021). "Subsequently, we conducted a mechanism study and found that DOP mainly acted on peroxisome proliferator-activated receptor-γ (PPAR-γ) signaling to regulate insulin sensitivity in diet-induced obesity (DIO) mice." (PMID 34194325, 2021). "Our laboratory investigated the effect of insulin resistance on mechanical pulmonary parameters and function in animal models of obesity." (PMID 33648564, 2021). "An SRA knockout transgenic mouse model (SRA−/−) displayed improved insulin sensitivity and resistance to developing obesity in high-fat diet conditions." (PMID 33572095, 2021). "Several studies have suggested that increased insulin secretion contributes to obesity pathogenesis by stimulating the adipocyte uptake of fatty acids and glucose and the caloric storage in form of fat, while concomitantly inhibiting lipolysis." (PMID 34680059, 2021). "Lipolytic activity in obesity is characterized by an overall increase with highly maintained basal lipolysis and a decrease in catecholamine-stimulated lipolysis by a defect in insulin-mediated suppression." (PMID 33505503, 2021). "Mst-knockout (Mst-KO) mice show significantly increased muscle mass, decreased fat mass, improved insulin sensitivity and resistance to diet-induced obesity." (PMID 33897620, 2021). "Literature about the role of Resistin in insulin sensitivity and obesity is controversial due to the difference between human and rodent resistin." (PMID 34209146, 2021). "miR-26a in β cells alleviated obesity-induced insulin resistance and hyperinsulinemia, and prevented hyperinsulinemia through targeting several critical regulators of insulin secretion and β cell proliferation." (PMID 33799467, 2021). "Animal models have demonstrated that sex and sex hormones can influence adipose tissue development, adipogenesis, gene expression profiles regulating insulin resistance and lipolysis, as well as the inflammatory tone and remodeling responses to obesity." (PMID 34371916, 2021). "All mentioned proteins act in the modulation of insulin sensitivity, and their levels are increased in cases of obesity and T2D." (PMID 34299048, 2021).
Obesity (continued). "In a diet-induced obesity model of male mice, we showed that treatment with Gracilex® improves insulin sensitivity by normalizing altered glucose and insulin parameters." (PMID 34071972, 2021). "A cooperative exchange of ghrelin and mediators associated with it, such as insulin, leptin, GIP, GLP-1, glucagon, and PAI-1, was revealed, which realizes their effects on obesity." (PMID 33959145, 2021). "In obesity, PPARγ activation diminishes ectopic lipid accumulation, reduces inflammation, and improves insulin sensitivity and lipid metabolism." (PMID 33536069, 2021). "At the level of adipose tissue, obesity induces the release of IL-1β by the tissue macrophages, which, in turn, inhibits insulin signaling in adipocytes and stimulates the release of adipocyte pro-inflammatory adipokines." (PMID 34299048, 2021). "Genetic associations with BMI were enriched in the networks of pancreas (BF = 2.07 × 1013), bowel (BF = 8.02 × 1012), and adipose (BF = 4.73 × 1012), consistent with the roles of obesity-related genes in insulin biology and energy metabolism." (PMID 33990562, 2021). "Ceramides are bioactive lipid metabolites that increase in metabolic tissues during obesity and induce cellular dysfunction via inhibition of the insulin, apoptotic and mitochondrial energy utilisation pathways." (PMID 34385976, 2021). "It was noted that plasma insulin levels were lower in animals on HFD compared to those on CD, which is contradictory to many studies that have reported increase insulin levels in obesity." (PMID 34439950, 2021). "In obesity, inflammatory signals appear to disrupt insulin action, leading to insulin resistance, and it has been hypothesized that the development of a systemic inflammatory state in those with overweight contributes to obesity‐associated pathophysiological consequences." (PMID 33491305, 2021). "TAAR1 agonist decreased food intake and body weight in a diet-induced model of obesity with improved insulin sensitivity and plasma triglyceride levels." (PMID 34943862, 2021). "Obesity and high levels of circulating FFA were also causatively linked to hampered insulin sensitivity in cells and compensatory hyperinsulinemia." (PMID 34930403, 2021). "This insulin–GH shift promotes energy storage and lipid synthesis and hinders lipid breakdown, resulting in obesity due to higher fat accumulation and lower energy expenditure." (PMID 34360563, 2021). "d-Allulose potentially ameliorates skeletal muscle insulin resistance during obesity through multiple mechanisms." (PMID 34684891, 2021). "In both humans and mouse models of obesity, the expression of the adipokine hormone adiponectin declines with obesity or increased BMI, and this reduction has direct consequences on the regulation of insulin sensitivity, satiety and inflammation." (PMID 34745014, 2021). "Obesity-induced chronic inflammation appears to negatively affect several insulin-sensitive tissues (e.g., adipose tissue, liver, and muscle) in individuals with IR and metabolic disorders." (PMID 34889901, 2021). "East Asian T2DM is becoming widely recognized as characterized primary by β-cell dysfunction and generally lesser obesity and higher insulin sensitivity compared with that in Caucasians." (PMID 34689790, 2021). "Obesity or high body mass index is a well-known condition where the sensitivity of insulin signaling is reduced in laboratory rodents." (PMID 34840459, 2021). "Obesity typically induces insulin resistance of the insulin-responsive peripheral organs which forces the pancreatic β-cells to increase their insulin secretion." (PMID 33880624, 2021). "Taken together, while constitutive heterozygous or homozygous postnatal ATX deficiency does not appear to alter energy homeostasis at baseline, it reduces adiposity/adipocyte size and improves glucose homeostasis and insulin function during obesity." (PMID 34502491, 2021). "BCAA catabolic enzymes are downregulated in adipose tissue both in obesity and in insulin resistence." (PMID 33772024, 2021).
Obesity (continued). "Irisin was reported to increase total energy expenditure, improve glucose tolerance and reduce fasting insulin level; therefore it improves glucose homeostasis, insulin resistance and obesity-related health conditions." (PMID 33905632, 2021). "Obesity phenotype induced insulin insensitivity but applied CR should reverse it, even resulting in higher insulin sensitivity." (PMID 33716957, 2021). "miR-143 is further induced by obesity and inhibits insulin-stimulated AKT phosphorylation in liver and adipose tissue of obese mice." (PMID 34943951, 2021). "We found skeletal muscle O-GlcNAcylation plays an essential role in systemic energy homeostasis, and the deletion of skeletal muscle OGT (mKO) protects mice from high-fat diet-induced obesity and ameliorates whole-body insulin sensitivity." (PMID 34326778, 2021). "In obesity-associated T2DM, decreased insulin sensitivity is the first lesion, ensued by elevated insulin levels." (PMID 33727637, 2021). "Chronic subclinical inflammation is a mechanistic link between obesity and IR, leading to alteration of insulin signalling in specific, key, metabolic districts such as the liver and adipose tissue." (PMID 35052584, 2021). "The possible beneficial effect of favoring adipocyte differentiation in the treatment of obesity was in part already suggested by the positive outcome on insulin resistance of PPARγ agonists, which act, among others, by promoting adipogenesis." (PMID 32157317, 2021). "In agreement, mice fed with a HFD exhibited a significant increase in obesity and lower glucose and insulin tolerance as compared to animals fed with a standard diet." (PMID 33916835, 2021). "In our previous work, we have defined miR-143-3p as an integrator of insulin signaling pathways in both MetS patients and mouse models of obesity." (PMID 34485272, 2021). "Preadipocyte proliferation rate negatively correlated with obesity and IR markers (BMI, glucose, insulin, and HbA1c)." (PMID 34545810, 2021). "PTPN6 is reported to show high expression in insulin target tissues in obesity, in which it interacts with P85, resulting in P85 dephosphorylation and reduced AKT phosphorylation in the control of liver metabolism; however, the mechanism is unclear." (PMID 33901186, 2021). "Four out of five observational studies established significant associations between Vit D level and four main components of MetS, namely dyslipidemia, insulin, glucose metabolism, obesity and BMI, and BP." (PMID 34589329, 2021). "For this reason, excessive TGs are released into the circulation as VLDL, significantly contributing to raised triglyceride levels in obesity and especially in insulin-resistant patients of patients with fatty liver disease." (PMID 34436472, 2021). "In mouse models of obesity and T2D, physiological doses of adiponectin enhanced insulin sensitivity." (PMID 34456860, 2021). "Insulin-stimulated signaling pathway is impaired in lymphocytes of individuals with obesity and Type 2 diabetes." (PMID 33390183, 2021). "In fact, pharmacological modulation and remodeling of adipose tissues ameliorated systemic insulin resistance and enhanced insulin-dependent glucose uptake by suppressing fat depot-related ATM in obesity." (PMID 34266493, 2021). "Glucagon-like peptide 1 (GLP1) is an incretin that enhances the secretion of insulin to reduce blood glucose levels; during obesity, intestinal epithelial lymphocytes can sequester GLP1 to limit its bioavailability." (PMID 33972511, 2021). "Both, obesity and body fat distribution are critical factors to decrease insulin sensitivity and B cells function." (PMID 33958606, 2021). "Resistin was first identified in rodents as an adipocyte-secreted factor that is upregulated in obesity and impairs glucose tolerance, insulin action, and fatty acid handling in skeletal muscle." (PMID 33528828, 2021).
Obesity (continued). "As a result, several obesity-related metabolism were improved, like lower serum glucose and insulin levels, increased insulin sensitivity, few hepatic steatosis and resistance to weight gain." (PMID 34992541, 2021). "Metabolic insults arising from obesity promote inflammation, which in turn can impair insulin signaling." (PMID 33806797, 2021). "Protein tyrosine phosphatase receptor gamma (RPTP-γ) has also shown to be a negative regulator of hepatic insulin signaling in physiological conditions, in obesity and in inflammation in mice." (PMID 34071721, 2021). "Adiponectin has been extensively studied for its involvement in insulin sensitivity, obesity and T2DM." (PMID 33716966, 2021). "1-Kestose also reduced plasma insulin concentrations in obesity-prone adults after a 12-week intervention, although the present clinical study included the limitation as the modest sample size." (PMID 34578862, 2021). "During obesity, nutrient storage capacity is dysregulated due to a reduced insulin action on its target organs, producing insulin resistance, an early marker of metabolic dysfunction." (PMID 34220716, 2021). "Given the close link between obesity and the development of PI3-K dysfunctional IR, it is important to explore how obesity mediates its effects on the insulin pathway." (PMID 33430419, 2021). "It has been elucidated that hypothalamic inflammation induced by fatty acids leads to obesity and it can induce insulin and leptin resistance which are involved in the regulation of food intake and obesity." (PMID 34611217, 2021). "On average, participants had been diagnosed with T2DM for 8 years, and 50% were on insulin medications, and the majority were in class 2 obesity (81%) and stage 2 hypertension per American College of Cardiology 2017 guidelines." (PMID 34901926, 2021). "The female DIO Western diet models (C57BL/6J) had free access to a high fat and sucrose-fructose and demonstrated obesity, insulin and leptin resistance, dysglycemia in the 150 to 200 mg/dL." (PMID 34063911, 2021). "This analysis reflects our previous study results, where we found women with obesity who received insulin to treat GDM had increased PL levels, which met and exceeded the levels detected in the otherwise healthy lean group of women." (PMID 33743677, 2021). "Our data suggested that the failure of pancreatic function (insulin therapy), overweight or obesity, and un-healthy life-style (smoking) were key to impact a global control of ASCVD risk factors." (PMID 34397707, 2021). "The aLrp1−/− mice are resistant to diet-induced obesity and are insulin sensitive with improved glucose tolerance compared with wild-type mice." (PMID 33500241, 2021). "In the case of lipid metabolism, it is known that in obesity, the impaired ability to up-regulate LPL by insulin exacerbates hepatic postprandial lipid load, thus causing hepatic steatosis." (PMID 33859314, 2021). "Adipocytes from these animals are multilocular, with enriched content in mitochondria, and display increased rates of β-oxidation, and these mice also exhibit improved insulin sensitivity and resistance to high-fat-diet-induced obesity." (PMID 34277603, 2021). "This insulin–GH shift hinders lipid breakdown and promotes further energy storage and lipid synthesis and thereby promotes obesity." (PMID 34360563, 2021). "Ostermann er al. showed that HFD-induced obesity increased insulin resistance in intestinal epithelial cells." (PMID 33827616, 2021). "Studies with liver-specific knockout mice have shown an overall glucose homeostasis improvement, including enhanced hepatic insulin signaling and increased suppression of hepatic glucose production in insulin-resistant and high fat diet-induced obesity models." (PMID 34203825, 2021). "In obesity, Treg, via modulation of inflammation, improve insulin sensitivity, lower blood glucose, and reduce end-organ sequelae." (PMID 34099626, 2021).